METTL3 (methyltransferase 3, N6-adenosine-methyltransferase complex catalytic subunit)
Diseases named in the same sentence as METTL3 in open-access papers (continued):
Sharing a sentence is not in itself a finding about the gene and the disease.
tumor (continued). "On another note, while studies are lacking assessing m6A regulated B cell dysregulation in TIME, B cells in the germinal center of a non-tumor model, are tightly controlled by METTL3 and METTL14, indicating their potential application in potential B cell targeted immunotherapy in the future." (PMID 37015927, 2023). "Moreover, in vivo experiments demonstrated that mice in the METTL3 overexpression group showed an obviously larger tumor size and tumor weight than the control group, while VGF knockdown inhibited METTL3 overexpression-induced tumor progression." (PMID 37742030, 2023). "Overexpression of METTL3 could effectively promote subcutaneous tumor growth in nude mice, while knockdown of METTL3 could inhibit subcutaneous tumor growth." (PMID 36710350, 2023). "Current studies have shown that METTL3 can participate in various tumor processes including AML." (PMID 37088992, 2023). "Among them, METTL3 can affect tumor progression by regulating the stability of lncRNA." (PMID 37088992, 2023). "The loss of the METTL3 gene in myeloid cells led to a reduction in the infiltration of exhausted CD8+ T cells, a decrease in the number of Treg cells, and an increase in the number of tumor-infiltrating CD8+ T cells." (PMID 38187373, 2023). "The impact of Mettl3 on tumor progression is mediated through numerous mechanisms." (PMID 37007040, 2023). "Moreover, the H&E pathological and Ki67 IHC staining revealed that mice implanted with either GEM-sensitive cells or GEM-resistant cells demonstrated significantly suppressed tumor aggression following METTL3 knockdown." (PMID 36977668, 2023). "Knockout of METTL3 in tumor-infiltrating myeloid cells (TIMs) including tumor-associated macrophages (TAM), tumor-associated neutrophiles (TAN), and MDSCs disrupts the immunosuppressive functions of myeloid cells in the CRC model, which is mediated by a METTL3-JAL1-STAT3 signal cascade." (PMID 37015927, 2023). "Thus, based on the potential opposed effects of METTL3 on tumour cells and normal cells, if targeting METTL3 or m6A to treat tumours, its side effects on normal cells should be carefully considered." (PMID 36564367, 2023). "However, the exact functional role of METTL3 in tumor promotion or inhibition is still controversial." (PMID 37151889, 2023). "Further in vivo study also demonstrated that METTL3 inhibition abolished the CAFs' stimulatory effect on tumor growth, suggesting that METTL3 could be a potential therapeutic target for NSCLC treatment." (PMID 37056933, 2023). "METTL3-mediated tumor cell growth is known to rely on MTC for its methyltransferase activity." (PMID 37589705, 2023). "Ablating macrophage METTL3 promoted tumor growth and lung metastasis." (PMID 35296338, 2022). "Meanwhile, METTL3 deletion markedly impeded Ki-67 activity in tumor tissues compared to controls." (PMID 36566195, 2022). "METTL3 was reported to have oncogenic or tumor-suppressor roles in a series of tumors." (PMID 36008805, 2022). "The recently characterized METTL3 inhibitor could affect RNA editing activity, contributing to its effect on tumor cells." (PMID 35886072, 2022). "Moreover, inhibition of METTL3 or IGF2BP3 enhanced anti-tumor immunity through PD-L1-mediated T cell activation, exhaustion, and infiltration both in vitro and in vivo." (PMID 35197058, 2022). "METTL3 inhibitor STM2457 also showed anti-tumor effect in ICC." (PMID 35094011, 2022). "In addition, it has been reported that the tumour suppressor miR-33a targets the 3′-UTR of METTL3 mRNA to reduce METTL3 expression, thus inhibiting A549 and NCI-H460 cell proliferation." (PMID 35518355, 2022). "METTL3 has been shown to function as an important gene to promote tumor progression." (PMID 36058919, 2022). "On the contrary, METTL3 played an anti-tumor role by COL3A1 and circMETTL3/miR-34c-3p in TNBC." (PMID 35721510, 2022). "Herein, we demonstrated that METTL3 facilitates tumor formation and CC progression." (PMID 35255776, 2022).
tumor (continued). "Moreover, stable knockdown of METTL3 reduced the metastatic capacity of the tumours assessed with the tail vein xenograft model." (PMID 35326563, 2022). "While YTHDF2, RBM15, ZC3H13, METTL3, HNRNPC, YTHDC1 with m6a modifications had higher expression in the low risk group, indicating that they might be tumor suppressors." (PMID 36199800, 2022). "GO analysis of biological processes suggested that METTL3 may affect tumor-related biological processes, such as vasculature development and cell proliferation, among others." (PMID 35595748, 2022). "In cervical cancer (CC), METTL3 was expressed much more highly in tumor tissues than in tumor-adjacent tissues, and its level was positively related to the density of CD33+ myeloid-derived suppressor cells (MDSCs), which in turn was linked to poor patient survival rate." (PMID 35296338, 2022). "COL10A1 secreted by CAFs could facilitate LUSC cell proliferation and repress apoptosis-induced oxidative stress, and the mechanism was due to elevated expression mediated by METTL3 promoting its mRNA m6A modification, thereby accelerating tumor growth." (PMID 36246404, 2022). "Abnormal expression of METTL3 in tumor cells affects the infiltration of immune cells." (PMID 35296338, 2022). "Functional analysis revealed that METTL3 is mainly involved in chromosomal homologous recombination and DNA mismatch repair processes, which could be potential mechanisms for tumor disease development and progression." (PMID 35574315, 2022). "The METTL3 inhibitor STM2457 also exhibits anti-tumor effect in ICC." (PMID 35094011, 2022). "Finally, we established the xenograft tumor model in nude mice to verify the role and mechanism of METTL3 in OS growth." (PMID 35396379, 2022). "Taken together, METTL3-induced FRAS1 promotes NSCLC tumor growth in vivo." (PMID 36008805, 2022). "Depletion of METTL3 in myeloid cells decreases tumor growth in mice." (PMID 36008936, 2022). "Meanwhile, as the therapeutic benefit of programmed cell death receptor 1 (PD-1) inhibitor was weakened in Mettl3−/− mice, METTL3 could be a potential target for tumor immunotherapy." (PMID 36035182, 2022). "Likewise, stable METTL3 overexpression significantly enhances tumor cell proliferation and invasion as well as tumor formation in nude mice." (PMID 35251990, 2022). "In prostate cancer cells, silencing METTL3 reduces the m6A modification of Gli1, an important component of Hedgehog pathway, and reduces the expression of Gli1, as well as the expression of downstream of hedgehog pathway, which promotes tumor cell apoptosis." (PMID 35022030, 2022). "Moreover, we also validated the expression of CDON, YTDHF1, and METTL3 in collected NSCLC tumor samples." (PMID 36008805, 2022). "In addition, methyltransferase 3, n6-adenosine-methyltransferase complex catalytic subunit (METTL3) affects the tumor formation by regulating the m6A modification in lncRNAs." (PMID 35441574, 2022). "It remains unclear if nuclear METTL3 is functionally distinct from cytosolic METTL3 in driving tumorigenesis and, if any, how tumor cells sense oncogenic insults to coordinate METTL3 functions within these intracellular compartments." (PMID 36289222, 2022). "METTL3 high status was negatively correlated with tumor immune cell infiltrations." (PMID 35813476, 2022). "METTL3-mediated m6A modification promotes tumour growth and metastasis by macrophage reprogramming." (PMID 35568866, 2022). "The subcutaneous transplantation tumor model confirmed that HHLA2 overexpression could reverse the inhibition of tumor growth mediated by METTL3 depletion." (PMID 35794583, 2022). "Depletion of METTL3 or METTL14 in tumor cells increased cytotoxic tumor-infiltrating CD8+ T cells and elevated secretion of IFN-γ, CXCL9, and CXCL10 in the TME, thereby enhancing the response to anti-PD-1 treatment in mismatch-repair-proficient or microsatellite instability-low CRC tumors." (PMID 35296338, 2022).
tumor (continued). "Furthermore, our data adds to the mechanism by which AC098934 affects tumor development, by highlighting the role of the m6A modification mediated by METTL3." (PMID 35711823, 2022). "Beyond METTL3 loss, a deficiency in Mettl14 or Ythdf2 in macrophages promotes the accumulation of EBI3 mRNA in an m6A-dependent manner, thereby triggering CD8+ T cell dysfunction, preventing CD8+ T cell infiltration, and accelerating tumor progression." (PMID 35254013, 2022). "Additionally, upregulation of METTL3 in tumors increases adenylate kinase-4 expression to promote mitochondrial metabolism-mediated tamoxifen resistance and tumor progression." (PMID 35794625, 2022). "In the third, 5-methylcytosine and METTL3-mediated m6A modification of lncRNA NKILA could accelerate the tumor growth and metastasis of CCA." (PMID 36476503, 2022). "In order to unravel the driving forces behind the markedly changed m6A patterns in the tumor adjacent tissues, we analyzed the expression of proteins related to coordinate m6A modifications by Western blot, including m6A methylation writers (METTL3, METT14) and erasers (FTO, ALKBH5)." (PMID 36172147, 2022). "METTL3 depletion in macrophages reshaped the TME by increasing M1- and M2-like tumor-associated macrophages (TAMs) and regulatory T (Treg) cell infiltration in vivo, resulting in tumor growth, metastasis, and drug resistance." (PMID 35331234, 2022). "The tumor growth rate was positively correlated with METTL3 expression." (PMID 35574388, 2022). "The METTL3 deficient mice decreases m6A methylation level of SPRED2, which can’t be recognized by YTHDF1, thus the reduction of SPRED2 translation leads to enhance NF-κB activation and promote tumor progression." (PMID 35022030, 2022). "The subcutaneous transplantation tumor model was used to study whether HHLA2 overexpression could reverse the inhibition of tumor growth induced by METTL3 depletion." (PMID 35794583, 2022). "In addition to its function as the catalytic core of the m6A writer complex, METTL3 can act explicitly as an oncogene, promoting HB proliferation while spurring tumor growth by virtue of its role in m6A modification." (PMID 35563821, 2022). "In addition, to the best of our knowledge, m6A-related AKR1B10 in cancer has not been reported; therefore, our study provides the first evidence that the tumor-promoting function of METTL3 is dependent on the m6A modification of AKR1B10." (PMID 36476503, 2022). "As PDK4 mRNA is also a target of m6A writer METTL3, ALKBH5 could antagonize lactic acid synthesis in tumor cells elicited by METTL3." (PMID 36289851, 2022). "Silencing of Mettl3 in macrophages facilitated tumour growth and lung metastasis." (PMID 36407103, 2022). "Therefore, interactions mediated by METTL3 and ncRNAs regulate the expression levels of post-transcriptionally regulated genes that determine tumor fate." (PMID 36035182, 2022). "In our study, increased translation of both oncogenic and tumor suppressor mRNAs was found in K177Q reconstituting cells, demonstrating the nuclear and cytosolic functions of METTL3 may act in concert with cell/tissue type in determining cell fate." (PMID 36289222, 2022). "Overall, this study identified that METTL3 high status, is associated with poor prognosis and HPV status, and serves as a mediator of the immunosuppressive tumor microenvironment in HPV-associated cancer, which provides a promising therapeutic target for anti-cancer immunotherapy." (PMID 35813476, 2022). "Second, it’s interesting that, based on our in vitro cellular investigation and in vivo tumor model study, we also demonstrated that overexpression of HHLA2 could significantly reverse the tumor inhibition mediated by METTL3 depletion." (PMID 35794583, 2022).
tumor (continued). "The reason for these contradictory findings may be explained by METTL3 playing different roles in the regulation of different pathways, but the METTL3-regulated pathways that contribute to a tumor-suppressing effect remain unknown." (PMID 35945641, 2022). "These experiments all indicate that METTL3 expression is increased in GC but through different pathways, which indicates that the same m6A-related protein might play a role in the same tumor via different mechanisms." (PMID 35155557, 2022). "While METTL14, WTAP, METTL3, ALKBH5, and YTHDC2 had lower expression in high risk group, indicating that they might be tumor suppressor." (PMID 35077391, 2022). "In our previous studies, METTL3 was found to be highly expressed in ESCA and may be potentially associated with glycolysis of tumor cells." (PMID 35401696, 2022). "By eliminating METTL3-mediated FOXO3 mRNA stabilization in the hypoxic tumor microenvironment, METTL3 depletion significantly enhanced the drug resistance of HCC to sorafenib, which confirmed FOXO3 as a crucial m6A modification downstream molecule in the sorafenib resistance of HCC." (PMID 36517820, 2022). "The tumor weight was markedly lower in the METTL3-knockdown group compared to the control group." (PMID 35094011, 2022). "Interestingly, the expression levels of METTL3 were downregulated in tumor tissues, while the KIF26B levels were significantly higher in tumor tissues than in matched non-tumor tissue." (PMID 35273176, 2022). "However, the expression levels of METTL3 were significantly positively correlated with the number of tumor neoantigens in STAD, HNSC, and PRAD." (PMID 36614956, 2022). "Based on our RNA-seq data analysis, EphA2 and VEGFA were enriched in growth and vasculature development in HCT116 cells; therefore, we evaluated the tumor‐promoting ability of METTL3 and its target genes, EphA2 and VEGFA, by upregulating EphA2 and VEGFA using a GV230 overexpression vector." (PMID 35595748, 2022). "Our results above reveal that METTL3 is very important for telomere stability in ALT cells, so we wondered whether loss of METTL3 affects the growth of ALT tumor cells." (PMID 36399511, 2022). "In addition, the effects of quercetin in existing literature reports have a lot in common with blocking METTL3, such as antitumor effect, reversal of tumor resistance, and antiviral effect." (PMID 35571106, 2022). "Lactate in the TME induces METTL3 expression in tumor-infiltrating myeloid cells (TIMs) through histone lysine K18 lactylation, METTL3 lysine K281 and K235 lactylation-mediated RNA m6A modification leads to tumor immune escape by promoting the immunosuppressive function of TIM." (PMID 36686771, 2022). "FRAS1 silence or YTHDF1 silence could rescue the elevated NSCLC cell proliferation, colony formation, and tumor growth induced by METTL3 overexpression in vitro and in vivo." (PMID 36008805, 2022). "We further verified whether STEAP2 inactivation was involved in the tumor inhibitory activity of METTL3 in PTC." (PMID 35436987, 2022). "The deletion of Mettl3 in myeloid cells promotes tumor growth and metastasis in vivo." (PMID 36225914, 2022). "Knockdown of METTL3 dramatically suppressed HeLa subcutaneous tumor growth in nude mice, as reflected by the significant reduction in tumor size and tumor weight, whereas METTL3 overexpression resulted in increased tumor size and tumor weight." (PMID 35637959, 2022). "Moreover, silencing METTL3 with siRNA enhanced the sensitivity of cancer cells to erastin treatments, and similarly for xenograft tumours in erastin‐treated mice." (PMID 35604883, 2022). "Our previous experiments demonstrated that METTL3 acted as a tumor gene in ESCC." (PMID 35399719, 2022). "methyltransferase-like 3 (METTL3) is a key member of the m6A methyltransferase complex that has recently been reported to play an important role in influencing angiogenesis and promoting tumor progression." (PMID 36114893, 2022).
tumor (continued). "Moreover, AKR1B10 was an m6A-related target of METTL3, and knockdown of AKR1B10 rescued the tumor-promoting effects induced by METTL3 overexpression." (PMID 36476503, 2022). "Depletion of METTL3 in myeloid cells promotes tumor growth and metastasis." (PMID 36008936, 2022). "Furthermore, tumor-related genes such as METTL3 and METTL3 have been identified as independent prognostic factors for OSCC." (PMID 35733916, 2022). "However, there are contrasting conclusions regarding the role of METTL3 as a tumor suppressor in CRC." (PMID 35155557, 2022). "We were curious if IL-6-mediated METTL3 acetylation contributes to tumor invasiveness." (PMID 36289222, 2022). "Nevertheless, the regulation of METTL3 on tumor cell metabolism, especially oxidative phosphorylation remains unknown." (PMID 36465351, 2022). "Besides, the expression of METTL14 and METTL3 at protein level were significantly upregulated in the tumor adjacent tissues." (PMID 36172147, 2022). "To investigate the function of METTL3 in vivo, we also performed tumor xenograft in nude mice." (PMID 35287752, 2022). "The result has shown that METTL3 overexpression is closely related to the prognosis of various tumors and could serve as a potential tumor biomarker." (PMID 35331234, 2022). "Diverse groups have demonstrated that METTL3 has either oncogenic or tumor-suppressive properties, which may be explained by tumor heterogeneity and/or diverse model systems used in the study, and further research is required to gain a better understanding." (PMID 36620557, 2022). "Studies have revealed that METTL3 plays vital roles in a variety of cancer types, either as an oncogene promoting the initiation and development of cancers or as a tumor suppressor in some cases, via different mechanisms depending on the specific type of cancer." (PMID 36077054, 2022). "It appears that METTL3 plays a dual role, which may be related to the tumor’s primary site of development, the cellular microenvironment, upstream and downstream regulatory elements, and resistance mechanisms." (PMID 36386128, 2022). "It was also reported that METTL3 can act as a tumor suppressor in some type of cancers." (PMID 35280730, 2022). "The differential expression of METTL3 across tumors has a dual role, which may reflect differences in targeting pathways and tumor heterogeneity." (PMID 35742899, 2022). "Also, the effects of METTL3 silencing and miR‐589‐5p mimic on tumour volume were reversed by each other." (PMID 35348293, 2022). "In breast cancer, the expression of METTL3 was positively correlated with the m6A expression level, both of which were up-regulated, which led to the upregulation of Bcl-2 expression, thus promoting tumour growth." (PMID 34794452, 2021). "We evidenced that METTL3 is overexpressed in tumor tissue compared to normal counterpart." (PMID 34530916, 2021). "In this study, we characterized that METTL3 contributes to Thymic Epithelial Tumor phenotype." (PMID 34530916, 2021). "In contrast, METTL3-deficient NK cells from tumor-bearing mice exhibited remarkably decreased protein expression of CD107a, GzmB and IFN-γ than METTL3-sufficient NK cells, indicating METTL3 deficiency-mediated inhibition of cytotoxicity and cytokine production of NK cells in the TME." (PMID 34535671, 2021). "Moreover, only ECA109 cells were used to establish the transplanted tumor model and lung metastasis model in vivo, although it is sufficient to confirm the role of METTL3 on other types of ESCA cell lines." (PMID 34666602, 2021). "On the mechanism, we found that circMETTL3 could act as a sponge for miR-34c-3p and inhibits cell proliferation, invasion, tumor growth and metastasis by up-regulating the expression of miR-34c-3p target gene METTL3." (PMID 35004298, 2021).